TLR2 (toll like receptor 2)
Diseases named in the same sentence as TLR2 in open-access papers (continued):
Sharing a sentence is not in itself a finding about the gene and the disease.
mastitis (48 papers, 2007 to 2025). Inflammation of breast tissue during lactation or postpartum due to an obstructed duct or infection. "The pathogenic mechanisms of mastitis involve the activation of Toll-like receptors (TLRs), specifically TLR2 and TLR4." (PMID 39199398, 2024). "The SNPs were identified among TLR2, 4, and 6 in mastitis-susceptible animals, with mutations in TLRs that were repeatedly reported in susceptible cows." (PMID 38922009, 2024). "TLR2 is associated with inflammation, apoptosis, and angiogenesis in various pathophysiological conditions in cattle (i.e., mastitis, endometritis, and enteritis)." (PMID 38338775, 2024). "The epithelial cells of the inner surface of the mammary gland play a key role in recognizing mastitis-causing pathogens by synthesizing toll-like receptors (TLR2 & TLR4)." (PMID 36911690, 2023). "The interaction between TLR2 and mastitis incidence was significantly associated with the fat (p = 0.02) and protein percentage (p = 0.04)." (PMID 35893772, 2022). "In contrast, the significant association of TLR2 with subclinical mastitis has been reported in Chinese Holstein cows and Egyptian Holstein cows." (PMID 35893772, 2022). "In conclusion, TLR2 is associated with inflammation, apoptosis, and angiogenesis in the MGs of dairy cows with bacteria-induced mastitis." (PMID 36142648, 2022). "In cattle and sheep, the various polymorphisms in TLR2 are associated with reduced SCC (Somatic Cell Count) or increased residence to mastitis." (PMID 32469968, 2020). "TLR2 is important for recognition of Gram-positive bacteria, which are the most common mastitis-causing pathogens in goats and TLR2 is therefore one of the crucial PRRs responsible for mammary gland immunity in small ruminants." (PMID 31396440, 2019). "Se, miR-146a and TLR2 were associated in determining the inflammatory response in mouse with infection-induced mastitis." (PMID 29340029, 2017). "As the HEK cell system is a somewhat artificial system, we next assessed the effects of SaTlp1 using pbMECs which express TLR2 and have been used before to assess the effect of mastitis causing pathogens on the innate immune response." (PMID 25538689, 2014). "Ruminant studies have demonstrated that TLR2 gene (designated as 'TLR2') expression occurs in dermal and gut-associated tissues, and is highly induced during mastitis caused by S. aureus." (PMID 18005441, 2007). "While bovine neutrophils might have evolved specific recognition mechanisms for different levels of pathogenic threat, mutations in the coding regions of TLR2, 4, and 6 genes elevated mastitis susceptibility, suggesting a crucial genetic link to resistance." (PMID 38922009, 2024). "The polymorphism of TLR2 in goats may be related to the elevated somatic cell count in milk caused by mastitis." (PMID 38714950, 2024). "TLR2 is observed to be strongly expressed during mastitis caused by S. aureus, which might be reflected in its ability to recognize the peptidoglycan and lipoteichoic acid from S. aureus and other gram-positive bacteria." (PMID 35893772, 2022). "Bioactive compounds and probiotics have been recognized as promising therapeutic agents for the prevention and treatment of mastitis by modulating the TLR2/TLR4/NF-κB signaling pathway." (PMID 40871398, 2025). "SLC11A1 was closely associated with the expression of genes involved in the regulation of the immune response and inflammation, with S100A12, NOD2, TLR2 and SPI1 being closely associated with mastitis resistance." (PMID 40427248, 2025). "We predicted a protein interaction network involving SLC11A1 interacting with 10 proteins, of which SPI1, NOD2, TLR2 and S100A12 have been reported as candidate genes associated with mastitis resistance." (PMID 40427248, 2025). "The expression levels of CORO1A and TLR2 mRNA and proteins were positively correlated with the incidence of mastitis." (PMID 40563467, 2025).
mastitis (continued). "In the context of mastitis, a prevalent inflammatory disorder of the mammary gland, the activation of toll-like receptors (TLRs), particularly TLR2 and TLR4, triggers the production of pro-inflammatory cytokines via the NF-κB signaling pathway." (PMID 40871398, 2025). "Based on the existing findings, it has been concluded that bioactive compounds targeting the TLR2/TLR4/NF-κB signaling pathways show promise in mitigating mastitis." (PMID 39199398, 2024). "This review summarizes recent research on the role of the TLR2/TLR4/NF-κB signaling pathway in mastitis." (PMID 39199398, 2024). "The in vitro investigations discussed in this review strongly support the idea that the TLR2/TLR4/NF-κB signaling pathway plays a crucial role in the development of mastitis in dairy cows." (PMID 39199398, 2024). "Recent in vitro studies have emphasized the importance of the TLR2/TLR4/NF-κB signaling pathway in the development of mastitis, suggesting its potential as a therapeutic target." (PMID 39199398, 2024). "Overall, this review highlights the significance of targeting the TLR2/TLR4/NF-κB signaling pathway to develop effective therapeutic strategies against mastitis, which can enhance dairy cow health and reduce economic losses in the dairy industry." (PMID 39199398, 2024). "A study documented that SNP T385G at exon 2 in the TLR2 gene is linked with high milk SCS and mastitis susceptibility." (PMID 36911690, 2023). "For instance, sequence analysis variations of the TLR2 and TLR4 genes were linked to endometritis and mastitis in river buffalo." (PMID 37756095, 2023). "The functions of TLR2 in milk components are perhaps rooted in its roles in mastitis and the health of animals." (PMID 35893772, 2022). "Some of the DEPs such as TLR2, STAT1 and Cathelicidins were associated with inflammation of dairy mastitis." (PMID 36003411, 2022). "This study is performed to test the association of TLR2 and LTF genes with mastitis incidence and milk components in the Holstein cattle breed raised in Vietnam." (PMID 35893772, 2022). "We also examined the association of polymorphisms in Lactoferrin (LTF) and Toll-like receptor 2 (TLR2) genes with mastitis score and milk component traits." (PMID 35893772, 2022). "This study examined the association of TLR2 and LTF polymorphisms with subclinical mastitis and milk components in the Holstein breed raised in Vietnam." (PMID 35893772, 2022). "Further studies using a larger sample size and/or DNA sequencing are required to confirm the roles in LTF and TLR2 genotypes in mastitis in the Holstein breed in Vietnam." (PMID 35893772, 2022). "Mechanistically, puerarin has been suggested to exert an anti-inflammatory effect by suppressing TLR2/NF-κB/JNK signaling in staphylococcus aureus-induced mastitis involving TLR2." (PMID 32457606, 2020). "The most in-depth mechanism showed that polydatin decreased the expression of TLR2 and MyD88, which further suppressed the level of NF-κB in mammary epithelial cells of S. aureus- induced mastitis." (PMID 32927884, 2020). "Ours results are in keeping with published data reporting a similar increase of CXCL8 mRNA expression in peripheral blood leucocytes of SCE cows 45–55 DPP and TLR2 mRNA in cows with mastitis." (PMID 31374089, 2019). "Toll-like receptor 2 (TLR2) signalling is responsible for recognition of Gram-positive bacteria, which are the most common mastitis-causing pathogens in goats." (PMID 31396440, 2019). "These reveal that TLR2 plays an essential role in the immune response of mammary epithelium and can be used as a candidate gene for clinical sheep mastitis, which deserves further study." (PMID 31417691, 2019). "However, our results showed that the mRNA and protein expression of CORO1A and TLR2 was abnormally upregulated during mastitis." (PMID 40563467, 2025).
mastitis (continued). "This temporal profile closely correlates with the clinical symptoms of mastitis: The upregulation of TLR2 and other receptors, along with the surge in pro-inflammatory mediators, directly triggers acute inflammatory responses in the mammary gland, manifesting as redness, swelling, heat, and pain." (PMID 41305370, 2025). "It ameliorates Staph. aureus-induced mastitis injury by attenuating TLR2-mediated NF-κB activation." (PMID 41012726, 2025). "Finally, we predicted the SLC11A1 protein interaction network and found that SPI1, NOD2, TLR2 and S100A12 interacted with SLC11A1 and were reported as candidate genes associated with mastitis resistance." (PMID 40427248, 2025). "Additionally, the review discusses various bioactive compounds and probiotics that have been identified as potential therapeutic agents for preventing and treating mastitis by targeting TLR2/TLR4/NF-κB signaling pathway." (PMID 39199398, 2024). "Toll-like receptor 2 (TLR2) is an important gene for mastitis resistance." (PMID 35893772, 2022). "Lactoferrin (LTF) and Toll-like receptor 2 (TLR2) have been suggested as candidate genes for mastitis; however, their associations with the mastitis incidence and milk components have not been reported in Vietnamese Holstein cows." (PMID 35893772, 2022). "Similarly, as TLR4 activation by LPS is protective against E. coli mastitis, this study aimed to boost TLR2-induced immune response of the murine mammary microenvironment by LTA to protect the host against S. aureus mastitis." (PMID 28791009, 2017). "It has been demonstrated that probiotics and bioactive compounds have the ability to modulate the TLR2/TLR4/NF-κB pathway, potentially reducing the inflammatory response and aiding in the prevention of mastitis." (PMID 39199398, 2024). "Based on available data, this review aims to summarize the research progress on the critical role of TLR2/TLR4/NF-κB signaling pathway activation in the prevention and treatment of mastitis." (PMID 39199398, 2024). "By targeting the TLR2/TLR4/NF-κB signaling pathway, we can potentially find a promising therapeutic approach to reduce mastitis." (PMID 39199398, 2024). "In terms of hub-hub genes, we identified several crucial immune and inflammatory response genes, including TLR2, TLR474, TNF, IL1β, IL1A, IL675, JAK276,77, and IL1068, which play important roles in the pathogen-host interactions during mastitis." (PMID 37620551, 2023). "More samples are required to validate the possibility of using TLR2 and LTF as biomarkers for subclinical mastitis incidence in the Holstein breed in Vietnam." (PMID 35893772, 2022). "We observed that the expression of TLR2 was double the expression of TLR4 in both neutrophils and macrophages during mastitis, which reflects the role of TLR2 in mediating an effective immune response against S. aureus." (PMID 34235202, 2021). "In this work, we explored the roles of TLR2 and TLR4 in S. uberis infections in TLR2−/− and TLR4−/− mice to further understand the molecular defense mechanism in S. uberis mastitis." (PMID 32098158, 2020). "A study proved, experimentally, that selenium restricts S. aureus-induced mastitis through inhibition of the MAPK and NF-κB pathways and TLR2." (PMID 32927884, 2020). "TLR2, NOD2, and inflammatory cytokines (TNF-α, IL-1β, IL-6, CXCL1, IL-10, TGF-β1, and IFN-γ) are involved in the response to mastitis induced by S. aureus." (PMID 25990971, 2015). "The present study aims to reveal the characteristics of TLR2, NOD2, and related cytokines in mammary glands against mastitis induced by S. aureus at an early stage in a rat mastitis model." (PMID 25990971, 2015). "The present study examined TLR2, NOD2, and related cytokines in mammary glands infection induced by S. aureus at early stages in a rat mastitis model." (PMID 25990971, 2015).
mastitis (continued). "The involvement of TLR signaling (particularly TLR2 and TLR4) in the host response to mastitis is well-documented; however, less is known about the involvement of the NLR and RIG-I pathways." (PMID 24470219, 2014). "In this study, as well as in others, TLR2 and TLR4 are characterized as being significantly influenced by E. coli mastitis." (PMID 21352611, 2011). "Among TLRs, TLR2 and TLR4 are particularly important in bacterial induced mastitis." (PMID 39199398, 2024). "Higher expression of TLR2 and TLR4 in neutrophil during mastitis might indicate higher recognition and elevated immune response against the microbes." (PMID 34235202, 2021). "TLR2 is an important member of the TLRs family that plays a crucial regulatory role in immune systems during diseases, and mastitis is no exception." (PMID 31417691, 2019). "TLR2 mRNA expression was shown to be higher in porcine mammary glands after inoculation with E. coli as well as in sows that developed clinical signs of mastitis than in the non-inoculated mammary glands of sows that remained clinically healthy." (PMID 25948480, 2015). "Moreover, CD40 and TREM1 signaling pathways appear as the most interesting candidates that likely provide the link between TLR2- and NLR-mediated signal transduction determining optimal host defence during mastitis." (PMID 24341851, 2013). "Similarly, another study reported that Brazilin (isolated from the traditional herbal medicine Caesalpinia sappan L.)suppressed TLR2, TNF-α, IL-1β, and IL-6 levels by inhibiting the TLR2/NF-κB/MAPK signaling pathways in mammary gland tissues, thus preventing S. aureus-induced mastitis." (PMID 39199398, 2024). "In addition to TNFa and IL-1b, CASP1 and NFKB1 were found to be up-regulated in our study suggesting that TREM1 signaling may likely provide the link between TLR2- and NLR-mediated signal transduction in cytokine-induced inflammation during the initiation of host defense such as in mastitis." (PMID 24341851, 2013). "TLR2 and NOD2 are important pathogen recognition receptors, but their functions have not been investigated in the context of early stages of mastitis." (PMID 25990971, 2015).
inflammatory bowel disease (47 papers, 2008 to 2026). A spectrum of small and large bowel inflammatory diseases of unknown etiology. "The peptidoglycan of L. casei YIT 9029, L. johnsonii JCM 2012, and L. plantarum ATCC 14,917 has been reported to suppress IL-12 production via Toll-like receptor 2 (TLR2), which is associated with autoimmune and inflammatory bowel diseases." (PMID 41316341, 2025). "Defects in TLR2 are associated with inflammatory bowel disease and inappropriate innate responses to intestinal tissue injury in mice." (PMID 25309051, 2014). "TLR2 polymorphisms have been associated with deficits in immune regulation such as inflammatory bowel disease, allergic asthma, and atopic disease." (PMID 25309051, 2014). "Our previous studies indicate that expression of TLR2 is higher in the airway mucosae of chronic otitis media patients than in normal subjects, and is also associated with inflammatory bowel disease (IBD) such as Crohn's disease." (PMID 18423053, 2008). "Moreover, mutations in TLRs, including the TLR2 gene, have been associated with predisposition to and maintenance of inflammatory bowel disease (IBD)." (PMID 28289440, 2017). "Increased TLR4 and TLR2 expression is also associated with both Inflammatory Bowel Disease (IBD) and CeD, implicating dysbiosis in disease pathogenesis." (PMID 31590358, 2019). "NCGS patients show higher levels of TLR2 compared to those with CD, causing dysbiosis similar to that observed in the pathogenesis of inflammatory bowel disease (IBD)." (PMID 30013742, 2018). "TLR2 signaling is also known to decrease intestinal permeability, a condition directly linked to inflammatory intestinal diseases such as celiac disease, inflammatory bowel disease (IBD), and irritable bowel syndrome (IBS)." (PMID 31623122, 2019). "Here we show that CD4+Foxp3+Tregs produce the effector cytokine IL-17A during oropharyngeal candidiasis (OPC) and inflammatory bowel disease in a TLR-2/Myd88 signaling dependent manner." (PMID 25790134, 2015). "Conversely, intestinal regulation and Treg levels were unchanged in TLR2−/− mice in a chronic model of inflammatory bowel disease." (PMID 25309051, 2014). "A growing body of evidence suggests that the Toll-like receptor 2 (TLR2) in the intestinal epithelium of patients with CRC or inflammatory bowel disease is up-regulated in comparison with healthy individuals." (PMID 23866094, 2013). "To define the role of TLR2 in the induction and regulation of chronic intestinal inflammation we examined the effects of TLR2 deletion on several complementary models of inflammatory bowel disease." (PMID 19950179, 2010). "Notably, ECs have IL-1β receptors and toll-like receptor (TLR)-2,4, indicating that ECs play a role in inflammatory diseases, such as inflammatory bowel disease (IBD)." (PMID 35370559, 2022). "In intestinal epithelial cells and dendritic cells, the expressions of pattern recognition receptors, such as Toll-like receptors (TLR)-2 and -4, along with some inflammatory cytokines (IL-18 and IL-1β), are increased in both irritable bowel syndrome and inflammatory bowel diseases." (PMID 30658440, 2019). "TLR2 appears to be a marker of inflammation in dogs, as demonstrated in the present study and in other canine inflammatory diseases, such as inflammatory bowel disease, immunomediated or bacterial arthritis, canine sino-nasal aspergillosis, and lymphoplasmacytic rhinitis or pyometra." (PMID 29547503, 2018). "However, under high 5-HT concentration, which is a condition that occurs in inflammatory bowel diseases, the level of TLR2 expression decreases, thus reducing TLR2 responses." (PMID 28033388, 2016). "The associations between toll-like receptor 2 (TLR2) and toll-like receptor 4(TLR4) polymorphisms and inflammatory bowel disease (IBD) susceptibility remain controversial." (PMID 26023918, 2015). "Recognized by TLR2, LAB can mitigate the development of inflammatory bowel diseases (IBD) and even suppress cancers." (PMID 36232768, 2022).
inflammatory bowel disease (continued). "A previous report showed increased expression levels of TLR2 and TLR4 in patients with inflammatory bowel diseases (IBDs), which are chronic inflammatory syndromes of the gastrointestinal tract." (PMID 30823938, 2019). "Furthermore, polymorphisms in genes encoding TLR2 and NF-κB signaling proteins (NFKB1 and NFKBIA) are associated with risk of inflammatory bowel disease (IBD)." (PMID 27563173, 2016). "In conclusion, enhanced TLR-2 and TLR-4 expression by crypt epithelial cells in active inflammatory bowel disease likely reflects greater ability to respond to microbial products." (PMID 24828022, 2014). "Indeed, human IECs constitutively express TLR3, TLR5, TLR9, NOD1, NOD2 and low levels of TLR2 and TLR4, where TLR4 is increased in inflammatory bowel disease (IBD) IECSs and intestinal macrophages." (PMID 36296363, 2022). "Oligosaccharide treatment increases TLR2 and TLR4 in inflammatory bowel disease." (PMID 30658440, 2019). "Furthermore, in the context of inflammatory bowel disease (IBD), enhanced serum levels of HMGB1 is accompanied by spontaneous IL-8 production by B-cells via interaction with TLR2 and CD36." (PMID 23519706, 2013). "Colonic IECs from patients with inflammatory bowel disease (IBD) have higher expression levels of TLR4 in particular, as well as lower levels of TLR2 and TLR5." (PMID 29438282, 2018). "Defect or damage in the TLR2 and TLR4 pathways can lead to sustained inflammation, characteristic of inflammatory bowel disease (IBD)." (PMID 25415606, 2014). "Furthermore, although the mechanisms are controversial, several studies report exacerbation of inflammatory bowel disease in the absence of TLR2." (PMID 25309051, 2014). "Cario and Podolsky analysed TLR2, TLR3, TLR4, and TLR5 protein levels in colonic biopsies and found that TLR4 protein levels were higher in both the inflamed and the noninflamed colonic mucosa of patients with inflammatory bowel disease compared to controls." (PMID 28246611, 2017).